RN7SL88P (RNA, 7SL, cytoplasmic 88, pseudogene)
Gene: Miscellaneous RNA gene on chromosome 12 (96,101,951 to 96,102,249, reverse strand). Ensembl gene ENSG00000277062.
Homologues: Orthologues: chimpanzee Metazoa_SRP (98% identical), macaque Metazoa_SRP (93% identical). Paralogues in human: RN7SL1 (86% identical), RN7SL2 (86% identical), RN7SL3 (85% identical), RN7SL126P (84% identical), RN7SL408P (83% identical), RN7SL296P (82% identical), RN7SL300P (82% identical), RN7SL301P (82% identical), RN7SL47P (82% identical), RN7SL664P (82% identical), RN7SL448P (81% identical), RN7SL498P (81% identical), and 705 more.